AGR3 (anterior gradient 3, protein disulphide isomerase family member)
Description:
Required for calcium-mediated regulation of ciliary beat frequency and mucociliary clearance in the airway. Might be involved in the regulation of intracellular calcium in tracheal epithelial cells.
Synonyms: AG-3; AG3; hAG-3; BCMP11; PDIA18; HAG3
Tractability: Antibody: UniProt predicts a signal peptide or a membrane-spanning region.
Gene: Protein-coding gene on chromosome 7 (16,859,412 to 16,881,987, reverse strand). Ensembl gene ENSG00000173467.
Subcellular location: Endoplasmic reticulum
Subcellular location (Human Protein Atlas): Endoplasmic reticulum; Vesicles
Gene Ontology:
Molecular function: dystroglycan binding; protein binding
Cellular component: endoplasmic reticulum
Genetic constraint (gnomAD): Loss-of-function variants: 19 observed, 12.27 expected, observed/expected ratio (o/e) 1.55, 90% interval 1.06 to 1.93. The upper end of that interval is the gene's LOEUF score, 1.93, which puts it in group 6 of 6, group 1 being the genes least tolerant of losing a copy. Missense variants: 111 observed, 99.11 expected, observed/expected ratio (o/e) 1.12, 90% interval 0.96 to 1.31. Synonymous variants: 34 observed, 30.82 expected, observed/expected ratio (o/e) 1.1, 90% interval 0.84 to 1.47.
Homologues: Orthologues: chimpanzee AGR3 (99% identical), macaque AGR3 (96% identical), mouse Agr3 (91% identical), rabbit AGR3 (90% identical), rat Agr3 (84% identical), tropical clawed frog agr3 (74% identical), Caenorhabditis elegans txdc-12.1 (27% identical), Caenorhabditis elegans txdc-12.2 (22% identical). Paralogues in human: AGR2 (63% identical), TXNDC12 (34% identical).
Diseases named in the same sentence as AGR3 in open-access papers:
AGR3 is named in the same sentence as 37 diseases in open-access papers, as found by Europe PMC text mining. Sharing a sentence is not in itself a finding about the gene and the disease. The quoted sentences say what the papers report.
breast carcinoma (25 papers, 2003 to 2025). "The present research confirmed the association of AGR3 with important features in the breast cancer clinic, such as hormone receptors, proliferation index, and prognosis." (PMID 37944928, 2023). "The top features in the BRCA-ER rSNFi signature include multiple genes known to be associated with breast carcinoma progression and outcome such as AGR3, B3GNT, and MLPH." (PMID 32714870, 2020). "The more specific roles of AGR3 in breast cancer and tumorigenesis were further investigated in a study by Obacz and colleagues." (PMID 40867591, 2025). "The authors found that extracellular AGR3 (eAGR3) promotes breast cancer cell adhesion and migration by participating in the c-Src signaling pathway and by inducing the phosphorylation of tyrosine kinases." (PMID 40867591, 2025). "The selective estrogen receptor modulator 4-hydroxytamoxifen also downregulated AGR3 in T47D breast cancer cells." (PMID 40867591, 2025). "For instance, AGR3 had already been characterized as a novel potential biomarker both for breast cancer prognosis and early breast cancer detection, while AGR2 expression has been correlated with poor outcomes of patients with ER-positive breast cancer." (PMID 39580456, 2024). "According to these precedents, the objective of the present systematic review and meta-analysis was to investigate the clinicopathological significance and prognosis of the expression of the AGR3 protein in women with breast cancer." (PMID 37944928, 2023). "Specifically, AGR3 promotes tamoxifen resistance in breast cancer, SRGN is a key molecule in mediating chemoresistance and stemness in breast cancer cells, and PPP1R1B is involved in resistance of breast cancer cells to trastuzumab." (PMID 37626402, 2023). "The Egger test ruled out the apparent bias in studies that analyzed the expression of AGR3 in women with breast cancer (p = 0.105)." (PMID 37944928, 2023). "The findings of the present study indicate that the expression of AGR3 was reduced for the triple-negative subtype of breast cancer." (PMID 37944928, 2023). "Fluorescently labelled AGR3 demonstrated that the protein localized in secretory or endosome-like organelles in the breast cancer cell line." (PMID 35965326, 2022). "For example, FOXA1 is known to segregate the luminal subtypes from the others, and AGR3 is a known biomarker for breast cancer prognosis and early breast cancer detection from blood." (PMID 34744522, 2021). "Other genes present in our MINT gene signature include XPB1, AGR3, CCDC170 and TFF3 that were reported as being associated with breast cancer." (PMID 28241739, 2017). "It is noteworthy that the majority of the analysed cancer sera were from low stage breast cancer patients suggesting a potential utility of AGR3 for early detection of breast cancer." (PMID 25875093, 2015). "In line, TCGA data analyses revealed an increased AGR3 mRNA expression in luminal breast cancer compared with basal-like tumours." (PMID 25875093, 2015). "Using a commercially available ELISA we demonstrated for the first time a significantly increased AGR3 protein serum concentration in sera from breast cancer patients compared to samples from age-matched healthy individuals." (PMID 25875093, 2015). "Initially, we demonstrated a clear up-regulation of AGR3 expression in human breast carcinomas compared to normal breast tissues on both mRNA and protein level." (PMID 25875093, 2015). "We determined the AGR3 protein level in an age-matched cohort of 40 serum pairs (i.e. 40 serum samples derived from breast cancer patients and 40 sera derived from healthy donors) using a commercially available ELISA kit." (PMID 25875093, 2015). "The current study is the first to analyse in depth the AGR3 expression, as well as its potential clinical relevance in breast cancer." (PMID 25875093, 2015). "In conclusion, our study suggests a putative prognostic impact of AGR3 in low (G1) and intermediate (G2) grade breast carcinomas." (PMID 25875093, 2015).
breast carcinoma (continued). "In the present study, AGR2 and AGR3 were identified for the first time as putative serum protein biomarkers in breast cancer." (PMID 25875093, 2015). "In sera analysed by ELISA technique, AGR3 protein concentration was significantly (P<0.001) elevated in samples from breast cancer patients (n = 40, mainly low stage tumours) compared to healthy controls (n = 40)." (PMID 25875093, 2015). "In conclusion, our data propose a pro-oncogenic impact of AGR3 in breast cancer, at least in well to moderately differentiated breast carcinomas." (PMID 25875093, 2015). "Using data of 516 breast cancer patients available at The Cancer Genome Atlas (TCGA) we found pronounced AGR3 mRNA expression in both PAM50 luminal subtypes, i.e. luminal A and B tumours, with a slightly stronger expression in luminal A carcinomas." (PMID 25875093, 2015). "To assess AGR3 expression data we initially performed a semi-quantitative AGR3 mRNA expression analysis of 62 breast cancer samples and 13 normal breast tissues." (PMID 25875093, 2015). "AGR3 has recently been described as up-regulated in breast cancer compared to normal breast tissues, while the putative clinical impact of AGR3 over-expression in breast cancer as prognostic or diagnostic protein biomarker remains elusive." (PMID 25875093, 2015). "Based on AGR3 protein level in serum samples, we were able to discriminate between breast cancer patients and healthy women with a sensitivity of 35% and a specificity of 92.5% (P < 0.01; AUC: 0.718 (95% CI, 0.606 to 0.830))." (PMID 25875093, 2015). "By performing receiver operating characteristic (ROC) statistics we further aimed to determine the clinical performance of AGR3 as a putative biomarker for breast cancer detection." (PMID 25875093, 2015). "Though up-regulation of AGR3 expression has recently been shown in breast cancer, its potential usability as a biomarker in this disease has remained elusive." (PMID 25875093, 2015). "AGR3 protein was originally identified as breast cancer membrane protein 11 (BCMP11), following a proteomic screen of membrane proteins in breast cancer cell lines, and was later named AGR3 due to the high degree of sequence homology with AGR2." (PMID 23245351, 2012). "BCMP11 (breast cancer membrane protein, also known as AGR3) was originally discovered by proteomics in breast cancer cell lines T-47D and MCF-7." (PMID 20021671, 2009). "Although emerging evidence suggests that AGR3 may contribute to the progression of ovarian and breast cancers, its precise role as an oncogene remains unclear." (PMID 40867591, 2025). "Similarly, the extracellular AGR3 is found to increase the migratory properties of ER-positive breast cancer cells MCF-7 and T-47D." (PMID 35159012, 2022). "AGR3 can also be secreted outside the cell as it was found to be secreted into blood serum and can be used as an independent prognostic factor for early screening of breast cancer patients." (PMID 35965326, 2022). "Furthermore, the same research group showed that AGR2 and AGR3 were both co-expressed in estrogen receptor (EsR)-positive breast cancer and can physically interact with LY6/PLAUR Domain Containing 3 (LYPD3 /C4.4a) and extracellular alpha-dystroglycan (DAG-1)." (PMID 35965326, 2022). "AGR3 protein was first identified in breast cancer cell lines." (PMID 33917163, 2021). "Moreover, we examined for the first time the putative prognostic relevance of AGR3 in breast cancer." (PMID 25875093, 2015). "Based on two independent tissue cohorts (n = 75 and n = 229) and one serum cohort (n = 80) of human breast cancer and healthy serum samples, we characterised AGR3 as a novel potential biomarker both for breast cancer prognosis and early breast cancer detection from blood." (PMID 25875093, 2015). "Therefore, we analysed the impact of AGR3 protein expression on patients’ outcome in 190 breast cancer samples." (PMID 25875093, 2015).
breast carcinoma (continued). "Moreover, AGR3 was found to be an independent prognostic factor of unfavourable prognosis in lower grade breast cancer cases, indicating a tumour-promoting function in well to moderately differentiated breast carcinomas." (PMID 25875093, 2015). "A combined integration of the here identified putative serum biomarkers AGR2 and AGR3 into a microfluidic-based analysing platform may help to improve breast cancer detection, hence to discriminate between healthy and disease status." (PMID 25875093, 2015). "Interestingly, concerning the distinct breast cancer subtypes, AGR3 expression was significantly higher in luminal breast cancer compared with the triple negative breast cancer cases." (PMID 25875093, 2015). "In light of the given over-expression of AGR3 in breast tumours associated with a potential prognostic impact, we subsequently assessed whether AGR3 protein concentration is increased in human serum samples of breast cancer patients as well." (PMID 25875093, 2015). "Indeed, we demonstrated a significantly increased AGR3 serum concentration (P < 0.001, median FC: 3.0) in breast cancer serum samples in comparison to control samples from healthy donors." (PMID 25875093, 2015). "AGR3 transcripts have been detected in lung and pancreas and, resembling AGR2, AGR3 has been reported to be co-expressed with estrogen receptor-α-containing breast cancer cell lines, suggesting it to be a marker for hormone-responsive breast cancer." (PMID 23245351, 2012). "Interestingly, despite its normally restricted expression, elevated AGR3 levels have been observed in estrogen receptor-positive breast cancers, both within cells and in secreted forms, raising the possibility that AGR3 acts as an ER foldase for cell surface receptors, analogous to AGR2." (PMID 40867591, 2025). "It has been demonstrated that AGR3 could be used for early breast cancer detection from blood." (PMID 36699355, 2022). "Its regulation of breast cancer cell migration and adhesion is executed by inducing the phosphorylation of tyrosine kinases such as Src as proved by the experiment that treatment with Dasatinib, a protein kinase inhibitor, remarkably reduces AGR3-dependent migration." (PMID 35159012, 2022). "It is also interesting to note that both the AGR2 and AGR3 genes are located side-by-side in chromosome 7p21 and are in close proximity to EsR binding sites, therefore it is not surprising that the genes are co-expressed particularly in EsR positive breast cancer." (PMID 35965326, 2022). "Additionally, AGR3 was proposed as a novel serum-based biomarker for breast cancer." (PMID 33917163, 2021). "Another implication is that four of the genes identified in this study—AGR2, AGR3, TFF3, and SCUBE2—have protein products that are secreted in the blood by breast cancer." (PMID 36836779, 2023). "AGR2 and AGR3 expression are coupled in EsR positive breast cancer and the combination of AGR2 and AGR3 as biomarkers resulted in increased sensitivity and specificity thus suggesting that they can be used as a prognostic factor." (PMID 35965326, 2022). "AGR3, also known as HAG-3, AG3, or BCMP11, was first identified in breast cancer cell membrane fractions using a proteomics screen." (PMID 34177583, 2021). "Thus our data clearly show the potential usability of AGR3 and AGR2 as biomarkers for blood-based early detection of human breast cancer." (PMID 25875093, 2015). "In human breast cancer, there have been no studies so far considering the putative biomarker potential of AGR3." (PMID 25875093, 2015). "Moreover, we demonstrate that both proteins AGR3 and AGR2 are detectable by ELISA technique at significantly elevated concentrations in sera from breast cancer patients compared with age-matched serum samples from healthy women." (PMID 25875093, 2015). "Hence, our findings clearly show for the first time the potential usability of AGR3 and AGR2 as biomarkers for non-invasive early detection of human breast cancer." (PMID 25875093, 2015).
breast carcinoma (continued). "Their study identified AGR3 as an estrogen-responsive gene through Gene Set Enrichment Analysis (GSEA) and demonstrated that AGR3 knockdown reduced cell viability, suggesting a role for AGR3 in promoting the viability of estrogen receptor-positive breast cancer cells." (PMID 40867591, 2025). "So far, the prognostic impact of AGR3 has not yet been investigated in breast cancer." (PMID 25875093, 2015). "Furthermore, AGR3 mRNA expression was significantly up-regulated (P < 0.05) in low (G1) and intermediate (G2) grade tumours compared to normal breast tissues, but not in high grade (G3) breast cancer cases." (PMID 25875093, 2015). "No significant differential AGR3 protein expression was observed between normal breast tissues and the HER2-enriched breast carcinomas." (PMID 25875093, 2015).
breast tumor (6 papers, 2003 to 2023). "AGR3 expression in breast tumours is significantly associated with oestrogen receptor α (P<0.001) and lower tumour grade (P<0.01)." (PMID 25875093, 2015). "Beside the potential prognostic relevance of AGR3 in G1 and G2 grade breast tumours, AGR3 is also an attractive serum based biomarker candidate." (PMID 25875093, 2015). "We conducted an immunohistochemical analysis for AGR3 using a tissue microarray consisting of 39 normal breast tissues and 190 breast tumours (see S2 Table for cohort characteristics)." (PMID 25875093, 2015). "AGR3 was predominantly expressed in the cytoplasm of breast tumour cells whereas only sporadic expression in single cells of the healthy breast epithelium was noticed." (PMID 25875093, 2015). "The Cox regression model confirmed AGR3 to be a putative independent marker of unfavourable prognosis in low and intermediate grade breast tumours (multivariate hazard ratio: 2.186, 95% CI: 1.008–4.740, P < 0.05)." (PMID 25875093, 2015). "We verified the increased AGR3 expression in breast tumour samples compared to normal tissues (median fold change (FC): 2.3)." (PMID 25875093, 2015). "The Cox regression model confirmed AGR3 to be a putative independent marker of unfavourable prognosis in G1 and G2 breast tumours." (PMID 25875093, 2015). "Our two‐gene (GATA3 and AGR3) IHC‐based panel could classify the histologic grade III ER+HER2− breast tumors into luminal‐like and non‐luminal‐like subtypes, for whom the benefit from endocrine therapy is limited." (PMID 34146382, 2022). "Furthermore, a highly significant (P < 0.001) over-expression of AGR3 protein in G1 and G2 breast tumours compared to normal breast tissues was detectable as well." (PMID 25875093, 2015). "Moreover, a correlation of AGR3 mRNA and protein expression with low and intermediate (G1 and G2) grade breast tumours was identified." (PMID 25875093, 2015). "Interestingly, AGR3 protein expression correlates with unfavourable outcome in low (G1) and intermediate (G2) grade breast tumours (multivariate hazard ratio: 2.186, 95% CI: 1.008-4.740, P<0.05) indicating an independent prognostic impact." (PMID 25875093, 2015).
colorectal cancer (5 papers, 2020 to 2025). A primary or metastatic malignant neoplasm that affects the colon or rectum. "It is also reported that AGR3 is responsible for the activation of the Wnt/β-catenin pathway in human colorectal cancer cells, which is an important mechanism for stemness and cell proliferation in cancer cells." (PMID 40265030, 2025). "A recent study showed that AGR3 can promote stemness of colorectal cancer by modulating Wnt/β-catenin signaling." (PMID 34177583, 2021). "For example, AGR3 has been shown to facilitate the stemness of colorectal cancer by regulating Wnt/β-catenin signaling; STC2 has been shown to be involved in resistance to treatment with EGFR tyrosine kinase inhibitors and to promote the progression of lung cancer by regulating JUN/AXL signaling." (PMID 33680908, 2020). "While the expression of AGR3 in the serous type of ovarian cancer predicts prolonged patient survival, AGR3 expression in colorectal cancer (CRC) predicts poor survival, which may be attributed to the ability of AGR3 to promote Wnt/β-catenin signaling and stemness in CRC cells." (PMID 40867591, 2025).